WDR82 (WD repeat domain 82)
Description:
Regulatory component of the SET1/COMPASS complex implicated in the tethering of this complex to transcriptional start sites of active genes. Facilitates histone H3 'Lys-4' methylation (H3K4me) via recruitment of the SETD1A or SETD1B to the 'Ser-5' phosphorylated C-terminal domain (CTD) of RNA polymerase II large subunit (POLR2A). Component of the PNUTS-PP1 protein phosphatase complex, a protein phosphatase 1 (PP1) complex that promotes RNA polymerase II transcription pause-release, allowing transcription elongation. PNUTS-PP1 also plays a role in the control of chromatin structure and cell cycle progression during the transition from mitosis into interphase. Together with ZC3H4, but independently of the SET1 complex, part of a transcription termination checkpoint that promotes transcription termination of long non-coding RNAs (lncRNAs). The transcription termination checkpoint is activated by the inefficiently spliced first exon of lncRNAs and promotes transcription termination of lncRNAs and their subsequent degradation by the exosome.
Synonyms: SWD2; TMEM113; WDR82A; PRO2730; MST107; MSTP107; PRO34047
Tractability: PROTAC: ubiquitination databases record sites on it; its protein half-life has been measured.
Target class: Reader; Epigenetic regulator; Methyl-lysine/arginine binding protein; WDR domain
Gene: Protein-coding gene on chromosome 3 (52,254,434 to 52,288,020, reverse strand). Ensembl gene ENSG00000164091.
Subcellular location: Nucleus; Chromosome; Cytoplasm
Subcellular location (Human Protein Atlas): Nucleoli rim
Pathways (Reactome):
Gene expression (Transcription): Formation of WDR5-containing histone-modifying complexes
Metabolism of RNA: Nuclear RNA decay
Gene Ontology:
Molecular function: protein binding; chromatin binding; lncRNA binding
Biological process: lncRNA catabolic process; negative regulation of DNA-templated transcription, elongation; negative regulation of lncRNA transcription; nuclear RNA surveillance; positive regulation of transcription elongation by RNA polymerase II; RNA polymerase II promoter clearance
Cellular component: chromatin; chromosome, telomeric region; histone methyltransferase complex; nucleus; PTW/PP1 phosphatase complex; Set1C/COMPASS complex; chromosome; cytoplasm; nucleoplasm
Genetic constraint (gnomAD): Loss-of-function variants: 7 observed, 29.96 expected, observed/expected ratio (o/e) 0.23, 90% interval 0.13 to 0.44. The upper end of that interval is the gene's LOEUF score, 0.44, which puts it in group 1 of 6, group 1 being the genes least tolerant of losing a copy. Missense variants: 172 observed, 382.58 expected, observed/expected ratio (o/e) 0.45, 90% interval 0.4 to 0.51. Synonymous variants: 125 observed, 134.6 expected, observed/expected ratio (o/e) 0.93, 90% interval 0.8 to 1.08.
Homologues: Orthologues: chimpanzee WDR82 (100% identical), dog WDR82 (100% identical), macaque WDR82 (100% identical), mouse Wdr82 (100% identical), rabbit WDR82 (100% identical), rat Wdr82 (98% identical), pig WDR82 (97% identical), tropical clawed frog twf2 (96% identical), guinea pig WDR82 (93% identical), zebrafish wdr82 (91% identical), Drosophila melanogaster Wdr82 (69% identical), Caenorhabditis elegans swd-2.2 (44% identical), and 1 more.
Diseases named in the same sentence as WDR82 in open-access papers:
WDR82 is named in the same sentence as 23 diseases in open-access papers, as found by Europe PMC text mining. Sharing a sentence is not in itself a finding about the gene and the disease. The quoted sentences say what the papers report.
lung carcinoma (7 papers, 2021 to 2024). "Another study showed that M2-EV miR-501-3p inhibits apoptosis by targeting WDR82 to promote the proliferation, migration, and invasion of lung cancer cells." (PMID 39896803, 2024). "Although WDR82 is typically underexpressed in tumor tissues, its overexpression in lung cancer cells has been observed to suppress the malignant transformation of these tumor cells." (PMID 39896803, 2024). "The authors showed that WD repeat domain 82 (WDR82) was a target of miR-501-3p, and the overexpression of WDR82 impaired the growth of lung cancer cells induced by M2 exosomes." (PMID 38002256, 2023). "Their study suggests that M2-derived exosomal miR-501-3p facilitates the proliferation, migration, and invasion of lung cancer cells via targeting WDR82." (PMID 38002256, 2023). "In this study, metformin significantly inhibited the expression of MLL1, MLL2, and WDR82 in lung cancer cells." (PMID 33578894, 2021). "Metformin suppressed the protein and mRNA expressions of euchromatic histone lysine methyltransferase 1, 2 (EHMT1, EHMT2), enhancer of zeste 1, 2 polycomb repressive complex 2 subunit (EZH1, EZH2), lysine methyltransferase 2A, 2B (MLL1, MLL2), and WD repeat domain 82 (WDR82) in lung cancer cells." (PMID 33578894, 2021).
colorectal cancer (5 papers, 2020 to 2022). A primary or metastatic malignant neoplasm that affects the colon or rectum. "WD repeat domain 82 (WDR82), an integral component of the SETD1A complex, is a key epigenetics-associated factor, and it has been unraveled that WDR82 is associated with progression and prognosis in human colorectal cancer." (PMID 33546686, 2021). "Primarily, miR-155-3p acts as an oncogene via the direct inhibition of tumour suppressors such as TP53INP1 (adenocarcinoma), FBXW7 (hepatocellular carcinoma), PCDH7/CREB3/SIX1 (glioma), WDR82 (colorectal cancer) and CADM1 (breast cancer)." (PMID 35611569, 2022). "It has been accepted that WDR82 reduction is correlated with a poor prognosis of patients with colorectal cancer (CRC), while the relationship of WDR82 with MB was little studied." (PMID 34983581, 2022). "Within colorectal cancer cells, miR-155-3p was found to directly inhibit WD repeat domain 82 (WDR82), a tumour suppressor which inhibits proliferation, migration, and invasiveness of colorectal tumours." (PMID 35611569, 2022).
medulloblastoma (4 papers, 2022 to 2024). A malignant, invasive embryonal neoplasm arising from the cerebellum. "M2-Exo miR-155-3p also enhanced the growth of medulloblastoma cells by targeting WDR82, thus accelerating medulloblastoma progression." (PMID 39896803, 2024). "This study was to investigate the role of miR-155-3p from M2 macrophages-derived exosomes (M2-Exo) in promoting medulloblastoma (MB) progression by mediating WD repeat domain 82 (WDR82)." (PMID 34983581, 2022). "In other studies, WD repeat domain 82 (WDR82) overexpression inhibited the metastasis of tumor cells, while miRNA-501-3p and miRNA-155-3p of M2-sEVs promoted the progression of LC and medulloblastoma (MB) by downregulating WDR82." (PMID 35832790, 2022).
bipolar disorder (1 paper, 2023). A disorder of the brain that causes unusual shifts in mood, energy, activity levels and the ability to carry out day-to-day tasks. "4/30 placental genes (TSTA3, BRD8, WDR82, SPG7) that were associated with both schizophrenia and bipolar disorder had opposite signs, so they were predicted to be up-regulated in the placentae of individuals who developed one disorder and down-regulated in the other disorder." (PMID 37188697, 2023).
glioblastoma (1 paper, 2023). The most malignant astrocytic tumor (WHO grade IV). "Elevated WDR82 and/or H3K4me3 is associated with therapeutic sensitivity in breast, cervical, and ovarian cancers as well as glioblastomas." (PMID 37444539, 2023). "WDR82 and/or H3K4me3 are associated with chemotherapeutic sensitivity in breast, cervical, and ovarian cancers, and adult glioblastoma cells." (PMID 37444539, 2023).
glioma (1 paper, 2023). A benign or malignant brain and spinal cord tumor that arises from glial cells (astrocytes, oligodendrocytes, ependymal cells). "A reduction in H3K4me3 by the downregulation of WDR82 decreased H3K4me3 promoter occupancy and gene expression and increased the response of pediatric glioma cells to chemotherapy." (PMID 37444539, 2023). "Here, we show that WDR82-mediated H3K4me3 is an important determinant of pediatric glioma malignancy and therapeutic response, and thus a potential epigenetic therapeutic target for children with malignant gliomas." (PMID 37444539, 2023). "The results highlight the necessity of a thorough understanding of the biological roles of WDR82 and H3K4me3 in pediatric glioma." (PMID 37444539, 2023). "Our results, showing that inducible reduction of WDR82 sensitizes the pediatric glioma cell response to cisplatin and radiation therapy, are also in line with alterations in gene expression observed in this work." (PMID 37444539, 2023). "A reduction in WDR82-mediated H3K4me3 increases the response of pediatric glioma cells to chemotherapy." (PMID 37444539, 2023). "The correlation between gene expression and WDR82 was plotted using RNA-seq results from pediatric glioma tissue specimens." (PMID 37444539, 2023). "In the group of genes with decreased expression, there was a correlation with WDR82 in pediatric glioma tissue specimens, and representative results are shown for NUP43 and PKYMT1." (PMID 37444539, 2023). "Investigation of its subunits WDR82, ASH2L DPY30 CXXC1, RBBP5, and WDR5 showed that WDR82 and WDR5 were significantly associated with WHO-grade malignancy in pediatric gliomas." (PMID 37444539, 2023). "Our data suggest that H3K4me3 status is an important determinant of pediatric glioma malignancy and therapeutic response, and that WDR82, which regulates H3K4me3, is a promising target to increase therapeutic efficacy and improve the prognosis for children with malignant gliomas." (PMID 37444539, 2023). "Reduction of WDR82 increased the response of pediatric glioma cells to chemotherapy." (PMID 37444539, 2023). "WDR82 is relatively high in glioma vs. other cancers, which is the sole subunit in SETD1A-COMPASS, specifically associated with pediatric glioma WHO-grade malignancy and patient survival, regardless of histone mutation status." (PMID 37444539, 2023). "Due to this specificity for pediatric gliomas, WDR82-mediated H3K4me3 is the focus of this study." (PMID 37444539, 2023). "The representative results showed WDR82 did not correlate with the expression of NUP62 and FBOX10, genes for which levels increased in pediatric glioma tissue specimens." (PMID 37444539, 2023). "Interestingly, in silico analysis results from The Cancer Genome Atlas (TCGA) show that WDR82 does not correlate with WHO-grade malignancy and survival in adult gliomas." (PMID 37444539, 2023).
Hyperglycemia (1 paper, 2022). An increased concentration of glucose in the blood. "We detected a significant increase in MLL2 and WDR82 in HUVEC exposed to intermittent hyperglycemia, and such treatment did not alter the protein level expression of SET1A, WDR5, SET1B, and MLL1(NT)." (PMID 35392173, 2022). "Intermittent hyperglycemia-dependent induction of partial mesenchyme-like phenotype of endothelial cells coincided with an increase in H3K4me3 level in both macro- and micro-vascular EC due to selective increase in MLL2 and WDR82 protein of SET1/COMPASS complex." (PMID 35392173, 2022).
leukemia (1 paper, 2022). A malignant (clonal) hematologic disorder, involving hematopoietic stem cells and characterized by the presence of primitive or atypical myeloid or lymphoid cells in the bone marrow and the blood. "To evaluate the roles of WDR82 complexes and cyclin K complexes in human leukemia cells, we performed a CRISPR functional assay against these complex subunits and confirmed the strong dependency on WDR82, cyclin K, and their binding partners." (PMID 36450243, 2022).
lymph node metastasis (1 paper, 2020). "The expressions of miR-224 and miR-147b were validated to be upregulated, while WDR82, PRPF4B and NR3C2 were downregulated in lymph node metastasis samples of TCGA datasets compared with non-metastasis samples." (PMID 33282547, 2020).
malignant glioma (1 paper, 2023). A grade III or grade IV glioma arising from the central nervous system. "This knowledge will establish if WDR82 and H3K4me3 are potential epigenetic targets to suppress tumor progression, increase therapeutic efficacy, and improve outcomes for children with malignant gliomas." (PMID 37444539, 2023). "This highlights the need for a more thorough understanding of the potential of WDR82 as an epigenetic target to increase therapeutic efficacy and improve the prognosis for children with malignant gliomas." (PMID 37444539, 2023).
tauopathies (1 paper, 2025). "Overall, RBPs enriched in disease-associated modules included the previously validated CHD4, MACROH2A1, SAFB, WDR82, and PAPOLA proteins, highlighting their potential relevance to tauopathies." (PMID 41205924, 2025).
cancer (7 papers, 2017 to 2024). A tumor composed of atypical neoplastic, often pleomorphic cells that invade other tissues. "WDR82 association with these genes is a novel finding; however, the results are consistent with discoveries in embryonic stem cells and various human cancer cells." (PMID 37444539, 2023). "In this regard, certain E3 ligases and other UPS components, such as the WD repeat-containing protein 82 (WDR82), have been identified as promising targets essential for various cancer cell types." (PMID 38607017, 2024). "WDR82 contributes to tumorigenesis, malignant phenotype, and tumor proliferation of multiple human cancers." (PMID 37444539, 2023). "In the area of CRC, it is described that WDR82 is lowly expressed in cancer patients, and knockdown of WDR82 is related to shortend overall survival and poorer outcomes." (PMID 34983581, 2022). "WDR82 activity is a key factor in maintaining embryonic and cancer stem cells." (PMID 37444539, 2023). "ECD, IL4R and WDR82 are protein coding genes, not commonly known to be associated with cancer risk or prognosis." (PMID 35444210, 2022). "The function of WDR82 and its family genes in cancers may indirectly verify our speculation." (PMID 33282547, 2020). "Also, WDR82 was predicted to interact with PPP2R2A; while PPP2R2A was reported to mediate inhibition of ERK and Akt pathways in cancer." (PMID 33282547, 2020). "LRRFIP2, WDR82 and ACOT1 were not identified previously as possible biomarkers for any type of cancer." (PMID 29285267, 2017).
tumor (7 papers, 2022 to 2024). "Increased WDR82 expression is associated with tumor malignancy grade." (PMID 37444539, 2023). "In humans, deletion of the WDR82, which is a homolog of ScSwd2, has been demonstrated to decrease H3K4me3 near the transcription start site of transcribed genes, and this deletion is associated with tumor progression." (PMID 37367608, 2023). "In combination, these results indicate that WDR82 expression is specifically relevant to the tumor biology of pHGGs." (PMID 37444539, 2023). "Inducible reduction of WDR82 decreases pHGG tumor cell growth in vivo and extends animal survival." (PMID 37444539, 2023). "On the other hand, miR-155-3p up-regulation in CRC could reduce the levels of WDR82, involving in the promotion of tumor progression." (PMID 34983581, 2022).
lymph node (1 paper, 2020). "The low expression level of WDR82 was associated with lymph node, liver metastasis and reduced OS." (PMID 33282547, 2020).
WDR82 also shares sentences with these, for which no sentence is quoted: colorectal tumours (1 paper); head and neck squamous cell carcinoma (1); heart defects (1); lung adenocarcinoma (1); myocardial infarction (1); ovarian carcinoma (1); pancreatic cancer (1); rectal cancer (1); schizophrenia (1).